RNU6-254P (RNA, U6 small nuclear 254, pseudogene)
Gene: Small nuclear RNA gene on chromosome 12 (19,445,949 to 19,446,055, reverse strand). Ensembl gene ENSG00000200247.
Homologues: Orthologues: chimpanzee U6 (99% identical), macaque U6 (93% identical), mouse Gm25618 (83% identical), dog U6 (82% identical). Paralogues in human: RNU6-38P (89% identical), RNU6-1145P (87% identical), RNU6-29P (87% identical), RNU6-831P (87% identical), RNU6-891P (87% identical), RNU6-1011P (85% identical), RNU6-1042P (85% identical), RNU6-25P (85% identical), RNU6-33P (85% identical), RNU6-359P (85% identical), RNU6-41P (85% identical), RNU6-468P (85% identical), and 1286 more.